SMAD4 (SMAD family member 4)
Diseases named in the same sentence as SMAD4 in open-access papers (continued):
Sharing a sentence is not in itself a finding about the gene and the disease.
fibrosis (8 papers, 2015 to 2024). the formation of excess fibrous connective tissue in an organ or tissue in a reparative or reactive process. "In conclusion, miR-452-5p regulates cardiac fibrosis progression by targeting the TGF-β/SMAD4 axis under the loss of the SCN5A gene." (PMID 38883840, 2024). "This suggests that targeting miR-452-5p/SMAD4 could offer promising therapeutic avenues for managing cardiac fibrosis in HF patients with SCN5A deficiency." (PMID 38883840, 2024). "In the present study, we utilized a lentiviral approach to silence the Smad4 gene in an in vitro fibrosis model of fibroblasts and an in vivo frozen shoulder model." (PMID 27351864, 2016). "The results of our study suggest that SMAD4-shRNA is able to reduce HSC-mediate fibrogenesis via down-regulation of hepatic fibrosis markers especially col1, α-sma and TIMP1." (PMID 26468346, 2015). "In the current study, the SMAD2, SMAD3, and SMAD4 mRNA expression levels were determined to be increased, and the SMAD7 mRNA expression level was decreased in the fibrosis control group." (PMID 39055873, 2024). "The SMAD2, SMAD3, and SMAD4 mRNA expression levels were increased and the SMAD7 mRNA expression level was decreased in the fibrosis control group." (PMID 39055873, 2024). "Several target genes of miR-26a and -26b have been identified for fibrosis thus far,including collagen I, CTGF, Smad4 and HMGA2.28,29, 30 Inthe current study, we uncovered a novel target gene Jagged-1 for miR-26a and -26b." (PMID 28622289, 2017). "Smad4 plays diverse roles in renal fibrosis and inflammation, suggesting Smad4 may not serve as the ideal therapeutic target for DKD." (PMID 33574750, 2020).
metastatic cancer (8 papers, 2015 to 2023). A carcinoma which has spread from the original site of growth to another anatomic site. "The canonical WNT-driven adenocarcinoma genetic requirements for invasion and metastasis consider SMAD4 a late-stage driver mutation for invasion and metastatic cancers." (PMID 38136364, 2023). "Disruption of TGFß signaling either by Smad4 or Tgfbr2 deletion in the background of a prostate specific tumor initiating mutation results in rapid progression to invasive and metastatic cancer in mouse models." (PMID 29782499, 2018). "PPP2R1A (E370X), SETD2 (I1608V), SMAD4 (G382T), and AR splicing site mutations were specific to liver metastatic cancer." (PMID 27023146, 2016). "TGF-β arrests cell cycle at G1 phase and initiates differentiation or apoptosis of normal cells; however, in metastatic cancer it is known to stimulate invasion and metastasis by up regulating the uPA mRNA and SMAD4 signaling 9,45." (PMID 25619880, 2015). "Many studies showed that Smad4 alterations were more frequent in advanced cancer and in metastatic cancers." (PMID 26527317, 2015). "We found that SMAD4 was highly expressed in the controls, indicated by the highest protein levels (+++), while its expression continually dropped during the progression from early tumors to metastatic cancers." (PMID 34381046, 2021). "In addition, another study showed that massively parallel sequencing coupled with dose-adjusted gemcitabine/carboplatin treatment of metastatic cancers with mutations in PDGFRA, SMAD4, and CDKN2A may lead to improved outcome." (PMID 32839457, 2020).
Obesity (8 papers, 2019 to 2025). Accumulation of substantial excess body fat. "The CC mouse GRP provides a unique platform and resource for studying BW complexity associated with obesity and BW gain influenced by the Smad4 knockout gene." (PMID 38003328, 2023). "In contrast, little is known about Smad4 in obesity or diabetes." (PMID 38003328, 2023). "Accordingly, we found that genes related to angiogenesis (e.g., ANGPT1, ANXA2), as well as to TGFβ signaling (e.g., SMAD4, BMPER, AKT2) are modulated in obesity condition." (PMID 30838002, 2019). "SMAD4 and RUNX2, which are components of TGFβ signals, became the second group of genes that increased their expression in adipose tissue of T2D– patients with obesity." (PMID 31866945, 2019).
polyp (8 papers, 2008 to 2026). A usually exophytic mass attached to the underlying tissue by a broad base or a thin stalk. "Of cancer and polyp specimens, 33.3% and 28.2%, respectively, were mutated in the Smad-4 gene." (PMID 35154600, 2021). "In this study, we used the genetically diverse Collaborative Cross (CC) mouse population crossed with Smad4 knockout mice to identify loci influencing intestinal polyp development." (PMID 42193864, 2026). "In a European retrospective study, polyps in the small intestine were even less common in BMPR1a DCV carriers (3.2%) compared to SMAD4 DCV carriers (15.7%)." (PMID 37400896, 2023). "In the present study, somatic SMAD4 mutations were found in 33.3% and 28.2% of analyzed specimens with CRC and polyp, respectively." (PMID 35154600, 2021). "DNA extraction and PCR-sequencing for exons 5-11 of the SMAD-4 gene were carried out on 39 and 30 specimens of polyp and adenocarcinoma, respectively." (PMID 35154600, 2021). "Inactivation of either of BMPR1A and SMAD4 is a crucial step in polyp development of JPS." (PMID 33327285, 2020). "To date, no attempt has been made to search for SMAD4 mutations in CRC or polyp in Iran." (PMID 35154600, 2021).
renal carcinoma (8 papers, 2015 to 2023). A carcinoma arising from the epithelium of the renal parenchyma or the renal pelvis. "Study has shown that the miR-452-5p expression is downregulated after sunitinib treatment and inhibits the migration and invasion of renal cancer cells by regulating the SMAD4/SMAD7 signaling pathway." (PMID 35465266, 2022). "Sunitinib therapy can regulate SMAD4 expression by altering the expression of Mir-452-5p in renal cancer." (PMID 36504560, 2022). "MiR-1260b binds to the 3′ untranslated regions (UTRs) of the DKK2, secreted frizzled-related protein 1 (sFRP1) and SMAD family member 4 (Smad4) mRNAs, thereby down-regulating their expression in renal cancer cells." (PMID 26656471, 2015). "Additionally, miR‐452‐5p promotes the invasion and metastasis of renal cancer cells by regulating the SMAD4/SMAD7 signaling pathways." (PMID 37014625, 2023). "Thus, genistein can downregulate miR-1260b that targets Smad4, or genistein can induce DNA methylation and histone modifications at Smad4 gene promoter in prostate and renal cancer cells." (PMID 34942997, 2021).
Telangiectasia (8 papers, 2020 to 2025). Telangiectasias refer to small dilated blood vessels located near the surface of the skin or mucous membranes, measuring between 0.5 and 1 millimeter in diameter. "Some patients and families with JPS and SMAD4 mutation exhibit a phenotype of HHT with epistaxis, telangiectasia and visceral AVM, particularly hepatic and pulmonary, without a genetic HHT mutation." (PMID 31971937, 2020). "SMAD4 + JPS patients should be evaluated for HHT within 6 months of diagnosis, examining for manifestations such as telangiectasia, AVM and digital clubbing." (PMID 38066625, 2023). "Hereditary Haemorrhagic Telangiectasia (HHT), Activin A Receptor Like Type 1 (ACVRL1), Mothers Against Decapentaplegic homolog 4 (SMAD4), Phosphatase and Tensin homolog (PTEN), Ras p21 protein activator 1 (RASA1), PIK3 CA and Ephrin 4 (EPHB4) testing were all negative for pathogenic mutation." (PMID 40490531, 2025). "In stark contrast, telangiectases seen in HHT patients with ACVRL1, ENG, or SMAD4 mutations are overwhelmingly punctate (not spidery) and typically occur on the lips and oral cavity, not other aspects of the face." (PMID 33834622, 2021). "Most patients with SMAD4-related JPS had HHT-manifestations including epistaxis, telangiectasias and AV-malformations (mainly pulmonary), this was not noted in patients with PV in BMPR1A and/or PTEN." (PMID 37354305, 2023).
viral infection (8 papers, 2011 to 2024). "In a recent study, it was reported that SMAD4 restrains the generation of CD103+CD8+ tissue-resident memory T cells after viral infection in the lungs." (PMID 35426367, 2022). "Among the 10 upregulated genes, several are involved in immune signaling of the viral infection, such as SMAD4, ATP binding cassette, HAUS8, FCH domain, ubiquitin peptidase 20, and heteronuclear Ribonuclear Protein C (hnRNP C)." (PMID 32526950, 2020). "Besides, we also found several instances including differentially expressed C4B gene and SMAD3/SMAD4/JUN/FOX complex to explore potential possible mechanistic details of how non-tumor individuals who are not susceptible fend off viral infections." (PMID 38752789, 2024). "Actually, Smad4 inhibits TGF-β-mediated conversion of ILC1-like cells from NK cells: Smad4 deficiency in NK cells does not affect ILC1 differentiation, but Smad4−/− NK cells acquire an ILC1-like gene signature and are unable to control tumor metastasis or viral infection." (PMID 36750317, 2023).
colon adenocarcinoma (7 papers, 2018 to 2025). "Other studies based on APC mutation, in combination with the inactivation of various members of the TGF-β family—such as TGFBR2, SMAD2, SMAD3 or SMAD4—resulted in the generation of invasive, but not metastatic, colon adenocarcinomas." (PMID 29652830, 2018).
colon adenoma (7 papers, 2017 to 2024). An adenoma that arises from the colon. "SMAD4 mutation is rarely detected in colon adenomas but occurs in intramucosal carcinoma and more commonly in invasive carcinomas with metastases." (PMID 28179590, 2017). "In the COSMIC database, 0.8% (2/246) of SMAD4 mutations have been reported in colon adenomas." (PMID 28179590, 2017). "Moreover, NK cell-specific Smad4 deletion promoted colon adenomas in DSS-treated ApcMin/+ mice and adenocarcinomas in AOM/DSS-treated mice." (PMID 33424832, 2020).
diabetes (7 papers, 2017 to 2024). "In the future, it would be interesting to use the advantages of heterozygous Smad4 knockout CC mice to investigate additional phenotypes of MetS, such as insulin resistance, diabetes, and lipid metabolism, in addition to cancer susceptibility." (PMID 38003328, 2023). "Moreover, we associated high concentrations of Smad4 plasma protein with the presence of diabetes, dyslipidaemia and hypertension in these patients." (PMID 32722512, 2020). "Thus, increased Smad4 levels were also a risk factor for a clinical diagnosis of diabetes (OR 1.301, 95% CI 1.071 to 1.580, p = 0.008), even after adjusting for age, sex, and BMI (adjusted OR 1.344, 95% CI 1.037 to 1.741, p = 0.025)." (PMID 32722512, 2020). "Dyslipidemia, which is often comorbid with diabetes, has been identified as a contributing factor to elevated levels of plasma SMAD4." (PMID 39335530, 2024). "In addition, the increased expression of lncRNA PVT1 in diabetic OA cartilage is also associated with Mankin score and reduced expression of type II collagen by negatively interacting with miR-146a, increasing the productions of inflammatory cytokines, and activating TGFβ/SMAD4 signaling pathway." (PMID 34874225, 2021). "We found that the cumulative incidence of diabetes by 30 weeks of age was 87.5% in female and 76.5% in male Smad4 tKO NOD mice, whereas it was 50% in female and 20.6% in male WT NOD mice." (PMID 27686408, 2017). "We found that T-cell-specific Smad4 deficiency in NOD mice accelerated and increased the onset of diabetes." (PMID 27686408, 2017). "In this study we generated T-cell-specific Smad4-deficient mice in NOD genetic background and investigated the role of Smad4-mediated signals in T cell function required for the development of diabetes." (PMID 27686408, 2017). "To investigate the effects of T-cell-specific Smad4 deletion on the development of type 1 diabetes, we assessed the cumulative incidence of diabetes by monitoring blood glucose levels in Smad4 tKO and wild-type (WT) NOD mice." (PMID 27686408, 2017). "Elevated levels of SMAD4 in people with diabetes may be attributed to the correlation between hypoxemia and diabetic acidosis, which has previously been shown to increase the expression of SMAD4." (PMID 39335530, 2024). "Therefore, inflammation in diabetes is the plausible and acceptable cause of increased levels of the proteins ACCS, GCSF, and SMAD4." (PMID 39335530, 2024). "All these data, together with the TGFβ canonical pathway by SMAD complex, support that SMAD4 might play an important role in the development of some OSA complications such as diabetes." (PMID 32722512, 2020). "Smad4 tKO showed earlier onset and increased incidence of diabetes than wild type (WT) NOD mice." (PMID 27686408, 2017). "In addition, Smad4 tKO NOD mice developed diabetes from 8 and 11 weeks of age in males and females respectively, whereas WT NOD mice developed diabetes from 15 and 12 weeks of age in males and females respectively." (PMID 27686408, 2017). "In the present study, ACCS, GCSF, and SMAD4 levels in T2DM were correlated with IR status, and their ability to diagnose diabetes mellitus state using neural network (NN) analysis was studied." (PMID 39335530, 2024). "More critically, SMAD4 expression has been reported to be down‐regulated in the articular cartilage of osteoarthritis patients, and TGF‐β/SMAD4 pathway activation alleviated the progression of diabetes‐related osteoarthritis." (PMID 39350476, 2024). "EMT and the TGF-β/Smad pathway were activated in the AECs of rats with COPD or diabetes, and the combination of COPD and diabetes amplified those effects, as indicated by downregulation of Zo1 and upregulation of vimentin, TGF-β and Smad4 in immunohistochemical experiments." (PMID 32369442, 2020).
diabetes (continued). "Depending on the low-grade inflammatory nature of diabetes, we investigated three proteins in T2DM patients: 1-aminocyclopropane-1-carboxylate synthase (ACCS), granulocyte–colony-stimulating factor (G-CSF), and Sma Mothers Against Decapentaplegic homolog-4 (SMAD4)." (PMID 39335530, 2024). "Finally, type 2 diabetic OSA patients also have higher plasma Smad4 levels than OSA patients without diabetes (702.2 ± 192.4 vs. 460.7 ± 248.1 pg/mL, p = 0.002)." (PMID 32722512, 2020).
leukemia (7 papers, 2014 to 2025). A malignant (clonal) hematologic disorder, involving hematopoietic stem cells and characterized by the presence of primitive or atypical myeloid or lymphoid cells in the bone marrow and the blood. "Although SMAD4 has been described as a tumor suppressor protecting from the leukemic transformation of HSPCs, only very few cases of SMAD4 mutations in leukemia have been reported." (PMID 39834944, 2024). "Moreover, some gene mutations are involved, and GATA2 and SMAD4 mutations were identified when the disease progressed from myelodysplastic syndrome to leukemia." (PMID 36181538, 2022). "Further investigation of Smad4 tyrosine phosphorylation and its physiological impact on other kinds of leukemia will reveal whether Smad4 tyrosine phosphorylation is a specific biomarker for different kinds of leukemia." (PMID 36959211, 2023). "Thus, the effects of BCR-ABL1 on TGF-β/Smad4 signaling may also exist in other BCR-ABL1-positive leukemia cells." (PMID 36959211, 2023). "Overall, in this study, we revealed that Smad4 phosphorylation by BCR-ABL1 plays an essential role in CML, which adds a novel mechanism to explain how TGF-β signaling is dysregulated in leukemia." (PMID 36959211, 2023). "Importantly, phosphorylation of endogenous Smad4 was detected in BCR-ABL1-positive K562 cells (lane 1) but not in BCR-ABL1-negative leukemia cells (lane 2–4)." (PMID 36959211, 2023).
osteoarthritis (7 papers, 2014 to 2024). A noninflammatory degenerative joint disease occurring chiefly in older persons, characterized by degeneration of the articular cartilage, hypertrophy of bone at the margins and changes in the synovial membrane. "The SMAD4 inhibition in osteoarthritis has also been documented, revealing the protective roles of SMAD4 against apoptosis and its pivotal roles in inducing the chondrocyte differentiation and proliferation." (PMID 34841647, 2022). "Overexpression of miR-146a in a model of osteoarthritis (OA) was accompanied by downregulation of Smad4 in vivo." (PMID 25161335, 2014). "According to the database of miRNA targets, miR‐3074‐5p might target SMAD4 during the course of osteoarthritis." (PMID 39350476, 2024). "Moreover, miR-145-5p regulates the proliferation and chondrogenic differentiation of BMSCs through targeting the Smad4 pathway in osteoarthritis." (PMID 37569358, 2023). "Therefore, SMAD4 is a key factor in chondrocyte apoptosis and osteoarthritis development." (PMID 39350476, 2024). "The absence of SMAD4 triggers cell apoptosis and escalates the progression of osteoarthritis." (PMID 39350476, 2024). "Furthermore, miR‐146a may make a contribution to osteoarthritis by increasing the VEGF levels and by suppressing SMAD4 in cartilage cells." (PMID 34841647, 2022).
thoracic aortic aneurysm (7 papers, 2018 to 2024). An aneurysm formed in the wall of the proximal portion of the descending aorta proceeding from the arch of the aorta. "A functional study by Ying Wang revealed that a variant of SMAD4 increased the risk of thoracic aortic aneurysms/dissections." (PMID 37183561, 2023). "Patients with SMAD4 pathogenic variants have also been found to develop thoracic aortic aneurysms and aortic dissections." (PMID 35685436, 2022). "To mimic the impact of rs12455792 - SMAD4 low expression generally, we constructed the SMAD4 KD mouse and detected the associated pathological progress of thoracic aortic aneurysm and dissection." (PMID 30530919, 2018). "Deletion of Smad4 in VSMCs led to the development of thoracic aortic aneurysm and subsequent death from aneurysm rupture in all affected mice, positing that Smad4 is integral to aortic wall homeostasis." (PMID 40337343, 2024). "Additionally, 202 thoracic aortic aneurysm/dissection cases were genotyped by five tagging SNPs of SMAD4, rs12455792, located in the 5′‐UTR of SMAD4, which is a binding site for TFs." (PMID 37183561, 2023).
vascular malformation (7 papers, 2020 to 2025). A non-neoplastic disorder that is the result of defects of vascular morphogenesis. "First, we performed manual analysis and variant calling of the sequencing data for the genes known to cause HHT (ACVRL1, ENG, GDF2, SMAD4) or vascular malformation syndromes with similar phenotypes (EPHB4, RASA1), as well as PIK3CA, which has been shown to modify vascular malformation phenotypes." (PMID 39062925, 2024). "Deletion of Eng or Smad4 also increased endothelial cell size, which might contribute to increased vessel diameter and vascular malformations." (PMID 36348215, 2023). "Genetic analyses of ACVRL1, ENG, and SMAD4 (in addition to EPHB4 and RASA1) are considered reasonable in all cases of high-flow intracerebral vascular malformations regardless of other HHT signs." (PMID 40259928, 2025).